AXL (AXL receptor tyrosine kinase)
Diseases named in the same sentence as AXL in open-access papers (continued):
Sharing a sentence is not in itself a finding about the gene and the disease.
breast carcinoma (continued). "We found upregulation in multiple genes associated with cancer growth and invasiveness, such as AXL, a tyrosine kinase receptor that mediates tumorigenesis and metastasis; AXL was recently suggested as a potential therapeutic target in breast cancer." (PMID 26040280, 2015). "High AXL expression in breast cancer is associated with reduced survival, and suppression of AXL prevented the initiation of ovarian metastases in mice; AXL gene expression was moderate to high in 4 of the 7 NCI-60 ovarian cancer lines." (PMID 22570691, 2012). "In breast cancer, AXL expression is driven by proteins associated with epithelial-to-mesenchymal-transition (EMT)." (PMID 23077658, 2012). "Indeed, it is currently recognized that AXL expression is associated with a higher risk of metastasis and an unfavorable prognosis of several solid cancers, such as breast cancer, non-small cell lung carcinoma, ovarian cancer, and clear cell renal carcinoma." (PMID 38391974, 2024). "For example, the receptor tyrosine kinase AXL,inferred for our method as the gene with the largest Relative CausalImpact, has been found to stimulate the phosphorylation of a network of focaladhesion (FA) proteins, promoting metastasis in breast cancer cells." (PMID 36124841, 2022). "However, anomalous AXL/Gas6 has been associated with tumour development, progression and reduced survival rate in number of malignancies, including breast cancer non-small cell lung cancer pancreatic cancer oesophageal cancer hippocampus neuron." (PMID 34140003, 2021). "Also, high AXL expression has been linked to chemoresistance in other cancers such as breast cancer, further supporting the notion that AXL expression promotes the survival of cancer cells." (PMID 33283192, 2020). "Hence, we investigated the role of the miR-34a–AXL axis on VM formation and invasiveness in breast cancer cells because the VM is closely associated with aggressive tumor features." (PMID 33374832, 2020). "Activation of AXL has also been implicated in EGFR inhibitor resistance in HER2+ breast cancer." (PMID 32148495, 2020). "AXL expression is also associated with increased tumorigenecity of breast cancer cells." (PMID 32148495, 2020). "Indeed, we and others have shown that the expression of AXL in human solid tumors is linked to a poor prognosis and is essential for metastasis in breast cancer models of TNBC and HER2+ subtypes in vivo." (PMID 31007848, 2019). "AXL is associated with drug resistance and metastatic spread of breast cancer." (PMID 29719832, 2018). "Importantly, analysis of clinical datasets revealed that high AXL expression is significantly associated with worse distant-metastasis-free survival (DMFS) in both breast cancer and TNBC, further supporting the clinical relevance of AXL as both a prognostic biomarker and a therapeutic target." (PMID 41009462, 2025). "Furthermore, it has been shown that crosstalk between diverse kinases may cause EGFR-TKI resistance, especially ligand-independent AXL activation in breast cancer cells." (PMID 27590506, 2016). "Together, our findings reveal a mechanoresponsive AXL-Arf1-Golgi signaling axis that integrates matrix stiffness sensing with Golgi organization and function in breast cancer cells." (PMID 41630693, 2026). "AXL receptor tyrosine kinase has exhibited elevated levels in breast cancer and induces tumour growth." (PMID 40560407, 2025). "AXL is thought to be a marker of TNBC since it is significantly expressed in TNBCs in comparison to all other breast cancers." (PMID 39755633, 2025). "A study on breast cancer stem cells revealed that c-Jun/AXL stress signaling contributes to chromosomal instability tolerance during tumor progression." (PMID 40092686, 2025). "To assess the prognostic significance of AXL, we analyzed 3911 breast cancer and 267 TNBC patients using the Kaplan–Meier plotter." (PMID 41009462, 2025).
breast carcinoma (continued). "Given the association between elevated AXL expression and reduced distant-metastasis-free survival (DMFS) in breast cancer and TNBC patients, we next investigated the impact of AB-329 on cell motility." (PMID 41009462, 2025). "Multiple compounds targeting AXL in breast cancer are currently under development, particularly in combination with immune checkpoint inhibitors." (PMID 41166388, 2025). "We also observed upregulation of AXL protein in stem-like breast cancer cell lines displaying gene expression similarities with aCSCs." (PMID 37809421, 2023). "AXL clinical relevance and oncogenic potential have been largely described, especially in breast cancer." (PMID 38132919, 2023). "In breast cancers, the heterodimerization of AXL and HER2 leads to the acquired resistance to anti-HER2 drug trastuzumab by activating AKT and ERK pathways." (PMID 37328828, 2023). "In breast cancer cells, AXL promotes RAC1-dependent invasion through phosphorylation of ELMO68, a scaffold for DOCK family RAC GEFs, while in glioblastoma cells AXL-dependent invasion involves PI3K and RAC1 activity." (PMID 37322019, 2023). "AXL inhibitors combined with adriamycin markedly decrease the tumor load as well as invasion and metastasis in adriamycin-resistant breast cancer." (PMID 37265798, 2023). "The catalytic activity of AXL induces endothelial tube formation in vitro and knockdown of AXL in breast cancer cells and in endothelial cell co-culture impairs this process." (PMID 35813203, 2022). "For example, AXL was found to correlate with metastasis in HER2+ breast cancer, a subtype that retains epithelial characteristics even though it often leads to metastasis and evidence suggests that EMT is required for this capacity." (PMID 35158733, 2022). "A similar observation was made using cells isolated from the PyMT murine breast cancer model and with MDA-MB-231 breast cancer cells where it was found that AXL inhibition post-seeding reduced the metastatic burden." (PMID 35158733, 2022). "Among all breast cancers, AXL is especially highly expressed in TNBCs hence regarded as a marker of TNBC81." (PMID 35414783, 2022). "TGF-ß exposure upregulates AXL expression and induces a mesenchymal-like phenotype in normal and immortalized human mammary epithelial cells, breast cancer (BCa) cells, and BCa cancer stem cells." (PMID 35572601, 2022). "The ATP-competitive inhibitors of AXL were reported to limit tumor progression by inhibiting cell activities and inducing apoptosis of breast cancer cells in animal models." (PMID 35414783, 2022). "AXL has been demonstrated to boost the motility, invasion, proliferation, and survival of breast cancer cells." (PMID 36186479, 2022). "R428, a selective AXL inhibitor, increases the survival rate of breast cancer patients by suppressing AXL." (PMID 36612193, 2022). "In a HER2+ breast cancer model, inducible AXL downregulation after the arrival of cancer cells in the lungs led to a reduction of metastatic outgrowth." (PMID 35158733, 2022). "The co-culture of AXL-CAR-T cells and AXL-positive breast cancer cells (such as MDA-MB-231) in vitro resulted in increased cytokine release and direct cancer cell lysis compared with AXL-negative cancer cells (such as MCF-7)." (PMID 35414783, 2022). "Previously, vimentin was reported to promote tumor metastasis through positive regulation of Axl (AXL Receptor Tyrosine Kinase) in breast cancer." (PMID 35359350, 2022). "In breast cancer cells, AXL pathway activation results in decreased expression and presentation of MHC class I antigens, leading to the decreased tumour infiltration by CD4+ and CD8+ T cells, and consequently, immune evasion." (PMID 34638349, 2021). "In our small cohort of relapsed breast cancers, high IHC positivity to AXL significantly correlated with metastasis to the lymph node." (PMID 33850249, 2021). "As for breast cancer, AXL predicted poor overall survival and was a crucial EMT-induced regulator of breast cancer metastasis." (PMID 34838035, 2021).
breast carcinoma (continued). "A similar positive correlation between vimentin and AXL expression was observed in breast cancer patients as well as in 92 breast cancer cell lines." (PMID 34638469, 2021). "This study tested patient-derived breast cancer tumors for AXL expression and found that patients with TNBC had the highest expression of AXL." (PMID 34729098, 2021). "Among all the members of TAM family, only AXL has been shown to be involved in the progression of various cancers including glioblastoma, breast cancer and CML." (PMID 34140003, 2021). "We confirmed that the overexpression of miR-34a in MDA-MB-231 breast cancer cells significantly decreased AXL expression at both the protein and mRNA levels." (PMID 33374832, 2020). "AXL-depleted murine breast cancer cells with breast cancer stem-cell-like properties were more sensitive to paclitaxel and etoposide compared to AXL-competent cells." (PMID 32148495, 2020). "In this review, we summarize the current knowledge of AXL functions and its implications in breast cancer progression." (PMID 33182542, 2020). "The membrane protein TIG1 binds and stabilizes AXL in breast cancer, preventing its proteasomal degradation leading to enhanced proliferative, migratory, and invasive abilities via activation of NF-κB and MMP-9." (PMID 32148495, 2020). "The promising results obtained in the preclinical field have led to the introduction of the pharmacological combination between AXL inhibitors and immunotherapy in various tumor contexts, including breast cancer, to bypass innate resistance." (PMID 33182542, 2020). "Despite not showing a significant effect on primary tumor formation, in a model of HER2+ breast cancer when metastasis formation was tracked, AXL knockout mice showed reduced lung metastases compared to controls." (PMID 32148495, 2020). "AXL inhibition by the small molecular drug R428 prevented metastasis and prolonged survival in breast cancer mouse models." (PMID 32992696, 2020). "In this study, we identified an miRNA-driven regulation of AXL expression and demonstrated its involvement in the regulation of AXL-mediated VM formation and invasiveness of breast cancer cells." (PMID 33374832, 2020). "In light of these activities multiple AXL inhibitors have been developed, and several of these have entered clinical trials in the U.S. In breast cancer, high levels of AXL expression have been observed." (PMID 32148495, 2020). "AXL has been shown to promote breast cancer cell motility, invasion, proliferation, survival, and anoikis resistance, often in conjunction with its role in EMT." (PMID 32148495, 2020). "In breast cancer AXL expression has been observed in all of the main transcriptional subtypes, and AXL expression in primary breast tumors is strongly predictive of reduced patient survival and poor outcome." (PMID 32148495, 2020). "Both the protein and mRNA expression levels of AXL in MDA-MB-231 breast cancer cells were substantially higher than those in the other breast cancer cell lines." (PMID 33374832, 2020). "In the MMTV-PyMT mouse model of breast cancer, AXL was observed to be upregulated in mesenchymal extravasated cells and to be important for activating lung fibroblasts in the stroma." (PMID 32148495, 2020). "Here, we report a novel function of AXL receptor tyrosine kinase (AXL) in the regulation of VM formation in breast cancer cells." (PMID 33374832, 2020). "To investigate the relationship between miR-34a and AXL functions in VM formation and invasiveness of breast cancer cells, we determined the effects of miR-34a overexpression on invasion, migration, and VM formation in AXL high-expressing breast cancer cells." (PMID 33374832, 2020). "In breast cancer, the metastatic process is finely regulated and AXL promotes cell invasion and migration." (PMID 33182542, 2020).
breast carcinoma (continued). "Given its highly oncogenic characteristics and its involvement in many pro-tumorigenic processes, currently, AXL is considered a valid biomarker in several tumor contexts, primarily breast cancer." (PMID 33182542, 2020). "Specifically, in breast cancer, AXL can be interact with its monomers present on neighboring cells or with other RTK family members." (PMID 33182542, 2020). "We found that AXL knockdown caused a significant decrease in the invasion and migration of MDA-MB-231 breast cancer cells." (PMID 33374832, 2020). "Further studies to investigate the mechanism involved in AXL-mediated VM are needed to fully elucidate the role of AXL in breast cancer." (PMID 33374832, 2020). "In breast cancer, cell transition to mesenchymal and invasive phenotypes is finely regulated, in several ways, by AXL." (PMID 33182542, 2020). "When miR-34a was overexpressed in MDA-MB-231 breast cancer cells with a high AXL expression, cell migration and invasion, which are essential for cancer metastasis, were inhibited." (PMID 33374832, 2020). "In this pathology, through uncontrolled activation of different downstream effectors, such as PI3K and MAPK, AXL regulates the malignant progression and migratory properties of breast cancer cells." (PMID 33182542, 2020). "Researchers have found that AXL mainly existed in the membrane of human breast cancer cells, and the expression of AXL in cancer tissues was much higher than in normal breast tissues from 23 normal human breast samples and 111 breast cancer tissue samples." (PMID 31998790, 2020). "GSK1016790A produced a general trend in EMT marker mRNA levels in PMC42LA breast cancer cells with significant increases in Snail, vimentin, AXL, SERPINE1, and CD44." (PMID 33322037, 2020). "In HER2- and ER-positive breast cancer cell lines, AXL promotes resistance to lapatinib and trastuzumab; for example, BT474 cells resistant to lapatinib show higher AXL levels as compared to the same control cells." (PMID 33182542, 2020). "Although it was demonstrated that miR-34a directly regulates AXL expression, the role of the miR-34a–AXL axis in the formation of VM in breast cancer cells remains to be investigated." (PMID 33374832, 2020). "In conclusion, we show that the modulation of AXL expression via miR-34a can manipulate VM formation and aggressiveness in breast cancer cells." (PMID 33374832, 2020). "MEK inhibition in breast cancer is associated with decreased cleavage of the extracellular domain of AXL by ADAM10/17, resulting in increased signaling through AXL." (PMID 32148495, 2020). "Taken together, these results suggest that miR-34a regulates invasiveness and VM formation via regulation of AXL expression in breast cancer cells." (PMID 33374832, 2020). "Decreased methylation of the AXL promoter was observed in lapatinib-resistant HER2+ breast cancer cells compared to sensitive cells, which correlated with higher levels of AXL expression in the resistant cells." (PMID 32148495, 2020). "Multiple tyrosine phosphorylation sites have been identified in the intracellular domain of AXL: Y698, Y702, Y703, Y779, Y821, and Y866, and three of these have been shown to be phosphorylated in breast cancer or breast cancer cell lines: Y698, Y702, and Y703." (PMID 32148495, 2020). "A recent pre-clinical study showed that in breast cancer, AXL expression is essentially regulated by miR-34a, which promotes the repressive activity only in selective genetic contexts." (PMID 33182542, 2020). "Originally, AXL was identified as a downstream target of EMT in breast cancer, whereby vimentin was shown to upregulate Slug and ultimately AXL." (PMID 32148495, 2020). "This mTORC1 activation in an AKT-independent manner is regulated by Serine/threonine-protein kinase 1 SGK1 in breast cancer, and by upregulation of AXL that activates mTORC1 via Protein kinase C (PKC ) in HNSCC." (PMID 33036331, 2020).
breast carcinoma (continued). "To assess the effect of AXL inhibition on VM formation in MDA-MB-231 breast cancer cells, we first assessed the siRNA knockdown effect by examining the protein and mRNA expression levels of AXL." (PMID 33374832, 2020). "Among breast cancer cell lines, AXL tends to be more expressed in TNBC, and more specifically in mesenchymal TNBC cells." (PMID 31963783, 2020). "In HER2-amplified breast cancer, AXL heterodimerization with HER2 allows its GAS6-independent activation and promotes drug resistance and tumor progression." (PMID 33182542, 2020). "AXL has been proposed as a potential therapeutic target for breast cancers and its inhibition sensitizes cells to chemo- or targeted-therapies." (PMID 31963783, 2020). "Zhang and collaborators have shown, on 21 breast cancer cell lines with different invasive capabilities, that AXL mRNA is particularly expressed in cells with invasive and aggressive phenotypes." (PMID 33182542, 2020). "In breast cancer, AXL’s activation, mediated by the link with GAS6, has been deeply studied, especially for its role in the connections between the tumor microenvironment (TME) and cancer cells." (PMID 33182542, 2020). "In a mouse model of HER2+ breast cancer, only slight differences were observed in tumor formation in AXL knockout mice compared to controls." (PMID 32148495, 2020). "We confirm that AXL is more expressed in mesenchymal TNBC cells compared to luminal breast cancer cells, and that its invalidation impairs cell migration while having no or little effect on cell viability." (PMID 31963783, 2020). "Next, we evaluated the expression level of AXL in seven breast cancer cell lines to investigate the correlation with VM formation." (PMID 33374832, 2020). "AXL has therefore been implicated in intravasation, extravasation, and maintenance of metastases in HER2+ breast cancer and in extravasation in other models of mammary tumors." (PMID 32148495, 2020). "High-level expression of AXL in mouse mammary tumors that were unresponsive to ionizing radiation in combination with immune checkpoint therapy has also been observed." (PMID 32148495, 2020). "A correlation was seen between the mesenchymal marker vimentin and AXL in both migratory cells at the wound edge in cell-based assays as well as in mammary tumors." (PMID 32148495, 2020). "The receptor tyrosine kinase AXL plays a role in tumor cell dissemination and its expression in breast cancers correlates with poor patient survival." (PMID 31007848, 2019). "In breast cancer cell lines, AXL expression is restricted to TNBC cells that display strong mesenchymal phenotypes." (PMID 31007848, 2019). "Breast cancer is the most prevalent cancer among women, and AXL and MET are the key genes in the PI3K/AKT/mTOR pathway as critical elements in proliferation and invasion of cancer cells." (PMID 30386383, 2018). "One of the principal factors in progression of cancers such as breast cancer is receptor tyrosine kinases, one of which is AXL, playing a part in PI3K and RAS signaling pathways." (PMID 30386383, 2018). "A multi-kinase AXL inhibitor has demonstrated restoration of sensitivity to both lapatinib and trastuzumab in a breast cancer model with acquired resistance to lapatinib." (PMID 28464908, 2017). "Taken together, this data suggests that KISS1, KISS1R and AXL are upregulated in invasive breast cancer cells (Hs578T, MDA-MB-231, SKBR3FLAG-KISS1R), compared to non or weakly invasive breast cancer cells (SKBR3, MCF7 and T47D)." (PMID 28422142, 2017). "On the other hand, it is involved in epithelial-to-mesenchymal transition in breast cancer by enhancing AXL-dependent activation of niche fibroblasts by the fibroblastoid tumor cells." (PMID 29176937, 2017). "Silencing of TGF-β inhibits invasion of breast cancer cells, mediated through reduction of the AXL levels." (PMID 29259259, 2017). "AXL is known to be an important regulator of EMT in breast cancer, neuroblastoma, and non-small-cell lung cancer." (PMID 29097911, 2017).